DUSP1 (dual specificity phosphatase 1)
Diseases named in the same sentence as DUSP1 in open-access papers (continued):
Sharing a sentence is not in itself a finding about the gene and the disease.
tumor (continued). "Most of the shRNA-DUSP1 tumors had relatively low levels of DUSP1, whereas one tumor showed high DUSP1 levels, possibly due to shorter doxycycline exposure or contamination with adjacent non-tumor tissue when harvesting the sample." (PMID 24409315, 2014). "In short, DUSP1 plays a complex role in many cancers in BC, higher levels of DUSP1 expression inhibit cell proliferation and promote apoptosis and act as a tumor suppressor." (PMID 41158869, 2025). "Inhibition of DUSP1 by DUSPi (inhibitor) in vitro induced OC cell death, and the study further demonstrates that the patient-derived xenograft (PDX) HGSOC model, inhibition of DUSP1 significantly inhibited tumor progression by differential regulation of AMPK and mTORC pathways." (PMID 41158869, 2025). "Consistently, subsequent studies showed that DUSP1 is expressed at low levels in normal breast tissue and ductal hyperplasia, while it is increased in carcinoma in situ and is overexpressed in approximately 50% of infiltrating BC tumours." (PMID 40943262, 2025). "As DUSP1 inhibition would utilize a different mechanism to kill cancer cells than traditional chemotherapies, combination therapies involving DUSP1 inhibition may reduce drug resistance and improve tumor regression." (PMID 41158869, 2025). "Among these upregulated genes, Dennd4a, Nfil3, Hspa1b, Chac1, Ddit4, Mex3b, Lysmd3, and Zbtb10 are mainly involved in oxidative stress and inflammation response, whereas Plcxd2, Dusp1, Cep85l, and Dusp8 are generally considered as tumor‐suppressor genes by inhibiting proliferation of cancer cells." (PMID 40231790, 2025). "Moreover, CDKN2B-AS1 suppressed CRC tumor growth, epithelial-to-mesenchymal transition (EMT), and induced apoptosis, whereas DUSP1 promoted CRC tumor growth and EMT by suppressing cell apoptosis in the CRC mouse xenograft model." (PMID 41158869, 2025). "The loss of DUSP1 expression is a characteristic of TSCs and is associated with the expression of tumor stem cell markers (ABCG2, NANOG, SOX2, PROM1, and L1CAM) in situ, which indicates that DUSP1 participates in the survival of these therapeutically resistant patients associated with GBM." (PMID 41158869, 2025). "Reduced DUSP1 levels in tumor cells may lead to hyperactivated MAPK, fueling tumor growth and metastasis." (PMID 41411347, 2025). "Third, the interplay between DUSP1 and other phosphatases or oncogenic pathways could modulate the net impact on tumor progression, requiring a more comprehensive systems-level analysis to fully appreciate the therapeutic implications." (PMID 41411347, 2025). "One plausible explanation is that CEBPB’s impact on the DUSP1 promoter may depend on additional cofactors or epigenetic changes present in the tumor microenvironment." (PMID 41411347, 2025). "Taken together, this substantial evidence strongly confirms that these HMDRGs (ZFP36, SERPINE1, AKAP12, CAV1, and DUSP1) are strongly involved in hypoxia, mitochondrial dysfunction, and tumor immunity, in turn contributing to the modulation of GC pathogenesis and prognosis." (PMID 39165353, 2024). "Considering the tumor suppressor roles of DUSP1 mediated by MAPK, and MAPK’s involvement in the Hippo pathway regulation, DUSP1 may regulate the Hippo pathway either via direct dephosphorylation of the Hippo component or indirectly through MAPK regulation." (PMID 38612874, 2024). "Sanders demonstrated that DUSP1 inhibition significantly inhibited tumor progression." (PMID 37476896, 2023). "DUSP1, a tumor suppressor, was reported to negatively regulate the ERK pathway." (PMID 37385985, 2023). "For example, the expression of genes such as JUN, FOS and DUSP1 showed an increasing pattern within the model and turned out to be high in both the tumor and normal samples, suggesting an involvement of these factors in tissue-specific differentiation processes." (PMID 37627150, 2023). "Among the selected transcripts, DUSP1 is a well-known tumor suppressor in HCC." (PMID 35453543, 2022).
tumor (continued). "In the present study, we illustrated the sROC curve, and the AUC of 0.91 indicated that DUSP1 could commendably distinguish OVCA tissues from non-tumour tissues." (PMID 35911442, 2022). "In addition, miR-101 improves the anti-tumor effect of sorafenib in HCC cells by targeting dual-specificity phosphatase 1 (DUSP1) and inhibiting TGF-β activation." (PMID 36071839, 2022). "The result of the subgroup analysis demonstrated that DUSP1 expression level was lower in OVCA tissues than that in non-tumour tissues (mRNA subgroup: SMD = −1.14, 95% CI [−2.13, −0.14], p = 0.025; protein subgroup: SMD = -1.52, 95% CI [−1.94, −1.10], p < 0.001)." (PMID 35911442, 2022). "Furthermore, we examined the relationship among DUSP1, tumour microenvironment (TME), and chemotherapy resistance in OVCA." (PMID 35911442, 2022). "Among the nine cohorts, four cohorts showed that the expression level of DUSP1 in OVCA was higher than that in non-tumour tissues, and the difference was statistically significant (TCGA_GTEx_OVCA, p < 0.0001; GPL570-OVCA, p = 0.0033; GSE11954, p = 0.0349; GSE155310, p < 0.0001)." (PMID 35911442, 2022). "DUSP1 acts as a tumor suppressor by negatively regulating MAPK activity in different tumors." (PMID 34336699, 2021). "Several studies have already shown the involvement of DUSPs as major modulators of critical signalling pathways dysregulated in different cancers, such as in the case of the overexpression of DUSP1/MKP-1 in the early phases of cancer and its decreasing during tumour progression." (PMID 31821333, 2019). "Indeed, significant down-regulation of MAPK3, MAP2K2, MAPKAPK3, ELK1 and up-regulation of the phosphatase DUSP1 was found in the reprogrammed tumours." (PMID 29662623, 2018). "The tumor suppression appeared to be mediated via the DUSP1-pERK/MAPK-MMP2 signal pathway." (PMID 28129656, 2017). "Our model identified mutations in VHL (von Hippel-Lindau), PBMR1, BAP1, MTOR, ATM, SETD2, KDM5C and PTEN (phosphatase and tensin homolog), as well as copy number changes in MLH1, DUSP1 and RANDBP17 as significantly associated with various TF activity changes across tumours." (PMID 28139702, 2017). "The partial response could be either due to partial down regulation of DUSP1 in knockdown cells or because DUSP1 pathway was part of multiple pathways involved in the anti-tumor effects of Gefitinib and MPA treatment." (PMID 29383165, 2017). "MPA treatment induces DUSP1 overexpression, which decreases tumor progression in EC." (PMID 29383165, 2017). "However, the consumption of fruit and soybean, and irregular menstruation significantly correlated with the DUSP1 methylation status of tumour DNA in both univariate and multivariate analyses." (PMID 28220843, 2017). "A significantly higher DUSP1 methylation frequency was observed in tumour DNA than in PBL DNA." (PMID 28220843, 2017). "Therefore, in this review, we will focus on the function and mechanism of DUSP1 in tumorigenesis, tumor progression, and antitumor therapy." (PMID 27227569, 2016). "DUSP1 plays different roles in different tumor stages and different cancers." (PMID 27227569, 2016). "However, in another study, DUSP1 was positively related to tumor angiogenesis in NSCLC patients and there is a statistically significant correlation between VEGFC and DUSP1 expression in these patients." (PMID 27227569, 2016). "In angiogenesis, DUSP1/MKP1 expression is associated with increased invasiveness of NSCLC due to an increased expression of VEGFC, suggesting that DUSP1 inhibition could be a good strategy to inhibit tumor invasion and angiogenesis." (PMID 24886454, 2014). "Moreover, DUSP1 negatively regulates ERK signaling in HCC cells, thereby inhibiting their proliferative potential, suggesting that DUSP1 is a tumor suppressor gene in HCC." (PMID 24409315, 2014).
tumor (continued). "Alternatively, CEBPB could modulate DUSP1 transcription in a context-dependent manner, activating expression in some conditions while simultaneously collaborating with other oncogenic signals to repress or override DUSP1’s tumor-suppressive functions." (PMID 41411347, 2025). "The limited data available to date suggest that DUSP1 dysregulation in tumors can lead to varied outcomes, including tumorigenesis, tumor progression, chemoresistance, radioresistance, immune escape, and tumor recurrence; however, in select cases, it can also have tumor-suppressing properties." (PMID 41158869, 2025). "Thus, we speculated that DUSP1 may control tumor differentiation through DUSP1-ERK/MAPK-AP1 feedback loop." (PMID 37057290, 2023). "In this study, we conducted a deeper investigation on molecular function of DUSP1 and confirmed that DUSP1 could affect tumor apoptosis, growth and invasion in EC using three EC cell lines originated from patients with different tumor stages and pathological grades." (PMID 37057290, 2023). "DUSP1 may play stimulative or suppressive roles in different types of tumours." (PMID 35911442, 2022). "In addition, DUSP1 may act as a tumour-suppressor in OVCA bye effecting TME and inhibiting MAPK signalling pathways." (PMID 35911442, 2022). "However, downregulated DUSP1 caused a substantial inhibition of NEU PKR−/− tumor growth in SCID mice as opposed to NEU PKR+/+ tumor growth, which was marginally affected by impaired DUSP1." (PMID 31086176, 2019). "Disappointingly, given that DUSP1/MKP-1 was both the first MKP to be discovered and also the first to be deleted from the mouse genome, there are currently no published studies in which DUSP1/MKP-1 has been directly implicated in either tumour initiation or progression." (PMID 30401534, 2019). "Interestingly, DUSP1 expression was lower in the tumor tissues than normal tissues." (PMID 28129656, 2017). "Besides, DUSP1 has been found to play a role in tumor chemotherapy, immunotherapy, and biotherapy." (PMID 27227569, 2016). "Besides, the role of DUSP1 in tumor therapy has been reviewed." (PMID 27227569, 2016). "Dual-specificity protein phosphatase 1 (DUSP1), a stress-responsive regulator of mitogen-activated protein kinase (MAPK) signaling, has emerged as a context-dependent modulator of tumor progression and therapeutic response in TNBC." (PMID 41744846, 2026). "In contrast, the downregulation or inactivation of DUSP1 in TNBC cells was shown to activate p38 MAPK and inhibit TNBC cell proliferation, migration, and tumor growth." (PMID 41158869, 2025). "Expression of DUSP1 negatively correlated with tumour differentiation, and, accordingly, both the phosphorylation and expression of ERK1/2 positively correlated with tumour differentiation." (PMID 40943262, 2025). "Like HCC, in gallbladder cancer (GBC), DUSP1 suppresses cancer cell proliferation/migration/invasion in vitro and inhibits GBC tumor growth and metastasis in vivo, when assessed in xenograft mouse models." (PMID 41158869, 2025). "Next, we examined DUSP1 expression in the TCGA COAD cohort and found it to be significantly lower in tumor samples compared with normal tissues." (PMID 41411347, 2025). "DUSP1 is the first member of the MAP kinase phosphatase (MKP) family, also known as MKP1, DUSP1/MKP1 is a dual-specificity phosphatase that regulates MAPK activity and plays a key role in tumor biology." (PMID 40535772, 2025). "DUSP1 knockdown in H460 cells impaired Matrigel invasion in vitro and suppressed tumor growth and metastasis in nude mice in vivo due to the decrease in VEGFC production, suggesting that DUSP1 is required for angiogenesis." (PMID 41158869, 2025). "In summary, our data indicates that DUSP1 and SOX2 have opposite functions in SG-SCC, being DUSP1 necessary for tumor growth and SOX2 dispensable showing a tumor suppressor function." (PMID 38951654, 2024).
tumor (continued). "The heatmap demonstrated SERPINE1 was up-regulated in tumor tissues, while the rest four genes (ZFP36, DUSP1, CAV1, and AKAP12) were down-regulated as compared to the normal group." (PMID 39165353, 2024). "The DUSP1/6 inhibitor BCI reduces cell viability in a dose- and time-dependent manner in a wide variety of tumor models, acting as an anti-tumorigenic agent, although it also exhibits pro-tumorigenic activity in other cellular models." (PMID 37776398, 2024). "Previous studies on DUSP1 were limited to its dephosphorylation of MAPK pathway members and its effect on tumor proliferation and progression." (PMID 37057290, 2023). "The results demonstrated that NOS3 and TCIRG1 were highly expressed in tumor cells and samples compared to normal cells and tissues, while GPX3 and DUSP1 were expressed at low levels in tumor cells and samples." (PMID 37124616, 2023). "We also proved EPHA2 is an important new target of DUSP1 and EPHA2 also plays an important role on tumor growth of EC." (PMID 37057290, 2023). "Across tumor types, HSD11B1 expression correlated positively with expression of the glucocorticoid-responsive genes TSD22D3 (GILZ), DUSP1, and FKBP5." (PMID 37471141, 2023). "Several hypoxia-related DEGs showed a highly correlated relationship to their expression levels in tumor samples, such as FOS and DUSP-1." (PMID 36675190, 2023). "Our results also validate that CA3, in combination with osimertinib, executes its anti-metastasis and pro-tumor apoptosis partly through autophagy and the YAP1/DUSP1/EGFR/MEK/ERK regulatory feedback loop in osimertinib-resistant cells." (PMID 37215986, 2023). "Dual-specificity phosphatases (DUSPs), such as MKP1 (DUSP1), dephosphorylate the serine/threonine residues of ERK to mediate tumor suppression." (PMID 38068984, 2023). "According to the in vitro data, sh-Tfeb D4M tumours showed reduced ERK1/2 activation, which was reported as the ratio of p-ERK1/2/ERK1/2 and an increase in DUSP-1 expression." (PMID 37160873, 2023). "In the present study, we demonstrated that the downregulated trend of DUSP1 protein in OVCA is based on clinical case analysis via IHC experiments (n of OVCA = 75, n of non-tumour = 45)." (PMID 35911442, 2022). "Most genes considered tumor specific in previous studies (tumor suppressor genes: SOCA3, KLF6, and PTGDS; tumor enhancer genes: SLC38A2, DUSP1, and FGF7) were expressed predominantly in tumor stroma or remission stroma than that in pre-treatment tumors." (PMID 36505794, 2022). "E2F1 binds directly to the promoter region of DUSP1 and activates its transcriptional activity, thus dephosphorylating MAP kinases, inducing apoptosis and suppressing tumour growth." (PMID 35844791, 2022). "Colorectal cancer tumor growth and metastasis was found to be enhanced by increased levels of oncogenic piR-1245 which is capable of binding and subsequently suppressing multiple tumor suppressors such as ATF3, DUSP1, and SESN2 by degradation of mRNA." (PMID 33673453, 2021). "In comparison with adjacent and precancerous tissues, we found a significant reduction of CD40+, CD27+, KLRB1+, and CCL5+ B cells (clusters 4, 9, 1, and 3, respectively) and MZB1+, DUSP1+, and CCL3+ plasma cells (clusters 5, 7, and 8) in tumor tissues." (PMID 34185431, 2021). "Previous studies suggested that DUSP1 can participate in JNK pathway activation and affect apoptosis and play a tumor suppressor role through the MAPK pathway." (PMID 32627968, 2020). "When DUSP-1 increases, JNK activation is counteracted, which consequently protects tumor cells from JNK-induced apoptosis." (PMID 33297397, 2020). "As a result of Dusp-1 increase, JNK activation would be inhibited, which consequently protects tumor cells from JNK‐induced apoptosis." (PMID 31506575, 2019). "Taken together, our study revealed that miR-96 is a tumor inducer of NSCLC and forms ceRNA regulatory network with FOXO1 and DUSP1 genes to co-regulate NSCLC development depending on EGFR signaling pathway." (PMID 31579447, 2019).
tumor (continued). "Downregulation of ATF4 in mouse NEU tumor cells by two different shRNAs reduced P21CIP1 and increased DUSP1, which was accompanied by decreased JNK1/2 phosphorylation." (PMID 31086176, 2019). "miR-96 can be considered as one of tumor-inducer and form competing endogenous RNA network with FOXO1 and DUSP1, which affects downstream EGFR signaling." (PMID 31579447, 2019). "In HCC, the expression of DUSP1 is inversely correlated with that of ERK1/2 and the proliferation rate and micro-vessel density, while DUSP1 directly correlates with tumor apoptosis." (PMID 31569678, 2019). "Among the upregulated genes in the tumors compared to those in the normal tissue, we found CKAP4, DUSP1, PAX8, AP1M2, C-KIT and NOTCH3, with NOTCH3 being the only gene that was upregulated in all tumor types." (PMID 31159852, 2019). "There are a further eight tumor-suppressor genes (DLEU2, CDKN2C, SPRY4, UBE2QL1, LIN9, TFPI2, LRIG3, DUSP1) and six genes serve as both oncogenes and tumor-suppressor genes (FOXO1, CAV1, KLF6, CDK6, PLK1, CTGF)." (PMID 30563222, 2018). "We also explored the correlation between clinicopathological characteristics and DUSP1 methylation in both tumour DNA and PBL DNA, as well as the effect of environmental factors on DUSP1 methylation in tumour tissue DNA." (PMID 28220843, 2017). "DUSP1/MKP1 is a dual-specific phosphatase that regulates MAPK activity and is known to play a key role in tumor biology." (PMID 28129656, 2017). "In this study, we analysed differences in DUSP1 promoter methylation between PBL DNA and tumour DNA." (PMID 28220843, 2017). "The most highly upregulated genes (e.g. CYR61, DUSP1, FOSB and FOS), which increased in almost all tumours, were early-response genes." (PMID 29214214, 2017). "We must highlight that DUSP1, DUSP4, and DUSP6 have pleiotropic roles as both oncogenes and tumour suppressors in various cancers." (PMID 26859151, 2016). "DUSP1 mainly promotes carcinogenesis by inhibiting phosphorylation of JNK in these cancers; however, it mainly inhibits the tumor progression by inhibiting phosphorylation of ERK." (PMID 27227569, 2016). "As a result of DUSP1 increase, JNK activation would be inhibited which consequently protect tumor cells from JNK‐induced apoptosis." (PMID 27227569, 2016). "Furthermore, qPCR results confirmed the microarray expression data of RGS1 and EEF1A1 in tumor ischemic colorectal tissue samples whereas differential expression of DUSP1, CYR61, SLC6A14 and DUOX2 in tumor ischemic colorectal tissue samples could not be validated." (PMID 26222051, 2015). "Although expression of CYR61, DUSP1 and RGS1 was detected, only RGS1 showed significant up-regulation in tumor tissue across all time points of ischemia." (PMID 26222051, 2015). "Other genes similarly regulated include DUSP1, EGR1, EGR2, JUN, and NR4A1, which are components of the TTP-low tumor gene signature, again linking TTP levels and innate immunity." (PMID 25541715, 2014). "We reported that DUSP1 is overexpressed in PDAC, and that antisense-mediated suppression of DUSP1 expression reduces tumor development in nude mice." (PMID 24409315, 2014). "It has been demonstrated, however, that hypoxia can upregulate DUSP1 transcription, and PDAC is a highly desmoplastic tumor with a markedly hypoxic microenvironment." (PMID 24409315, 2014). "Many anticancer drugs regulate DUSP1 expression and immune invasion in TME; for example, sorafenib, a common drug used for HCC treatment, apart from multi-kinase inhibition, sorafenib exposure in HCC modulates anti-tumor effect via macrophages." (PMID 41158869, 2025). "Recent single-cell transcriptomic analyses have revealed distinct DUSP1 expression patterns in cancer stem-like cells within TNBC tumors, highlighting its involvement in promoting survival under stress and contributing to tumor plasticity." (PMID 41158869, 2025).